CCL2 (C-C motif chemokine ligand 2)
Diseases named in the same sentence as CCL2 in open-access papers (continued):
Sharing a sentence is not in itself a finding about the gene and the disease.
cancer (continued). "Specific flavonoids can attenuate the TNF-α-induced release of MCP-1/CCL2 and various recruiting cytokines from cancer cells." (PMID 34950252, 2021). "Cancer cells secrete monocyte chemotactic factors (mainly CCL2) to recruit monocytes/macrophages to the TME." (PMID 35008577, 2021). "Macrophage recruitment by CCL2 has been reported in various malignancies, and there is a correlation between macrophage infiltration into cancer tissues and increased CCL2 expression." (PMID 34445235, 2021). "CCL2 is mainly secreted by Schwann cells that first arrive at the sites of cancer cells and bind to the CCR2, promoting proliferation, migration, invasion, and epithelial–mesenchymal transition (EMT)." (PMID 34441243, 2021). "CCL2 and CCR2 can function as diagnostic biomarkers, and are correlated with the prognosis and poor overall survival in cancer patients." (PMID 34464477, 2021). "Here, we show that microenvironmental cytokines, particularly CCL2, decorate cancer exosomes via binding to surface glycosaminoglycan side chains of proteoglycans, causing exosome accumulation in specific cell subsets and organs." (PMID 34112803, 2021). "Recent research showed that chemokines and cytokines, namely, TNF-α, IL-6, and chemokine (C-C motif) ligand 2 (CCL2), have roles in the formation of the cancer microenvironment and are responsible for the migration of inflammatory cells and cancer cells." (PMID 34631699, 2021). "During the study, the authors noted that fucoidan treatment inhibited CCL2/MCP-1 secretion in HCT 116 cancer cells treated with LMW fucoidans." (PMID 34940677, 2021). "TAM recruitment is highly linked to the CCL2/CCR2 axis, and in many cancer models, blocking this axis has led to a significant decrease in TAM populations." (PMID 34209703, 2021). "Here, we review works focusing on the interactions between cancer cells and host cells, and on the biological role of CCL2 in these processes." (PMID 34386431, 2021). "A co-culture of primary squamous lung carcinoma cells with MSCs led to the secretion of CCL3 by cancer cells and an elevated expression of IL-6, CCL2, ICAM-1, and VCAM by MSCs." (PMID 34950592, 2021). "During cancer progression, cancer cell-derived CCL2, CCL5, CXCL8, and CXCL5 are released and recruit immunosuppressive-myeloid cells into the TME, including MDSCs, TAMs, and TANs through CXCR2 activation." (PMID 35127700, 2021). "One of those is the chemokine C-C ligand 2 (CCL2), which has been shown to play a key role in both cancer and stromal cells." (PMID 34948097, 2021). "CCL2 promotes the infiltration of monocytes, thus promoting cancer-cell vascularization, extravasation and metastasis." (PMID 34164400, 2021). "Cancer-bearing mice were found to have increased the expression of CCL2 in cancer cells and the infiltration of MDSCs into cancer tissues; blocking CCL2 decreased MDSC, both in serum and in tissues, and improved their prognosis." (PMID 34445235, 2021). "Cancer cells release factors (G-CSF, GM-CSF, CCl2, etc.)to convert myeloid cells into immunosuppressive phenotypes (e.g., MDSC, myeloid-derived suppressive cells, or M2 macrophages)." (PMID 34298755, 2021). "The secretion of CCL2 and CXCL cytokine subfamily cause the infiltration and M2 conversion of macrophages in the cancer niche, leading to the immune escape and long-distance metastasis." (PMID 34098945, 2021). "The HMC3 cells were stimulated with a cytokine cocktail known to originate from cancer cells, that was comprised of interleukins IL-4, IL-13, IL-10, growth factors TGFβ1/TGFβ2, and chemokine CCL2." (PMID 34566949, 2021). "Considering other CC subfamily chemokines, CCL2 and CCL5 have also been implicated in the progression of a wide range of cancers." (PMID 34206004, 2021). "CCL2 is a chemokine and a chemotactic factor for monocytes and had been reported to be increased in many cancer types." (PMID 34592589, 2021).
cancer (continued). "The interaction of cancer cells with endogenous TRAIL induces FADD-dependent secretion of CCL2, which polarizes monocytes to the M2 macrophage phenotype." (PMID 34371753, 2021). "The association between low and high expression of CCL2 or CCR2 and cancer prognosis has been studied for several human diseases." (PMID 34944943, 2021). "Here, we demonstrated that repeated i.t. injection of INCB3344 exerted anti-allodynic effects, as previously observed in neuropathic, postoperative, and cancer-induced bone pain models using anti-CCL2 antibodies or small molecule antagonists of CCR2." (PMID 33757529, 2021). "CCL2, monocyte chemoattractant protein 1 (MCP-1/CCL2), is recognized for its role involved in cancer progression and drug resistance 38-40." (PMID 33664852, 2021). "Specific immune cells mobilized into cancer tissues by chemokines, such as CCL2, undergo various changes when stimulated by cancer cells or stromal cells." (PMID 34445235, 2021). "In tissues rich in αSMA and FAP, CCL2 and IL-6 secretion is increased, leading to cancer progression." (PMID 34445235, 2021). "In contrast, Bonapace L showed that discontinuation of anti-CCL2 treatment in mice models significantly accelerates cancer metastasis through regulation of TAMs recruitment." (PMID 34580284, 2021). "An example of this is CCL2/MCP-1, which causes apoptosis resistance and chemoresistance of cancer cells against anti-cancer drugs." (PMID 32781743, 2020). "We used high-throughput antibody array to screen the signals mediating the interaction of nerve cells and cancer cells and found the high expression of CCL2 in dorsal root ganglion (DRG)." (PMID 32064233, 2020). "For this reason, it is postulated to administer additional drugs to disrupt the function of CCL2 during cancer therapy." (PMID 33182504, 2020). "In primary squamous lung cancer, statins break the communication between cancer cells and mesenchymal stromal cells (MSCs) by inhibiting CCL3 secreted by cancer cells and IL-6 and CCL2 produced by MSCs." (PMID 32843638, 2020). "Together, MYC and Twist1 induce the cancer cell to secrete cytokines like Ccl2 and Il13 that lead to recruitment and polarization of macrophages respectively, thus causing metastasis." (PMID 31933479, 2020). "In particular, therapeutic blockade of CCL2-CCR2 interaction by using CCL2 neutralizing antibodies or CCR2 antagonist has demonstrated promising antitumor efficacies in several preclinical cancer models." (PMID 32849585, 2020). "In particular, microenvironment-derived CCL-2 can recruit MDSCs to cancer sites via CCL2-CCR2 interaction." (PMID 32391020, 2020). "Consistent with previous results, the cancer-promoting capacity of TAMs was significantly impaired by Wnt5a knockdown, which was reversed by recombinant CCL2 treatment." (PMID 32140070, 2020). "In another cohort, the expression of CCL2 was markedly enhanced in cancer tissues when compared to the paired para-cancer tissues." (PMID 32103760, 2020). "The role of CCL2 in cancer progression has gradually been understood, and various preclinical cancer models elucidate that CCL2 and its receptor C-C chemokine receptor 2 (CCR2) are attractive targets for intervention in cancer development." (PMID 33297571, 2020). "Inhibition or blockade of the CCL2/CCR2 signaling axis has thus been an area of interest for cancer therapy." (PMID 33247183, 2020). "Interruption of the CCL2–CCR2 axis can suppress EMT and prostate cancer cell migration and invasion, providing a critical mechanism linking CCL2 and cancer metastasis." (PMID 33297571, 2020). "As for mode of action, it appears plausible that NAM acts as a therapeutic agent by re-establishing T cell-dependent immunosurveillance via both direct (T cell activation) and indirect (type I IFN and CCL2 secretion by cancer cells) mechanisms." (PMID 32732875, 2020).
cancer (continued). "Elevated expression of CCR2 and MMP9 in ZEB1 wildtype F4/80low macrophages provided a positive feedback loop with ZEB1 wildtype cancer cells through cancer cell-expressed CCL2 cytokines." (PMID 32283687, 2020). "Although the roles of CCL2 in cancer progression have been understood gradually, drugs modulating the CCL2–CCR2 axis as anticancer agents are clinically not available except for administration in clinical trials." (PMID 33297571, 2020). "Collectively, these data suggest that Wnt5a mediates the cancer-promoting functions and macrophage recruitment of TAMs via CCL2." (PMID 32140070, 2020). "Previous studies have revealed that CCL2 secreted by the nerves facilitates pancreatic ductal adenocarcinoma invasion by binding to its receptor (CCR2) expressed on the membrane of cancer cells or macrophages." (PMID 32064233, 2020). "There is a number of studies suggesting that CCL2 can activate cancer cells through a variety of mechanisms." (PMID 33297571, 2020). "This suggests that CCL2 not only maintain chemoresistance in drug-resistant tumoral cells but also confer drug resistance to drug-sensitive cancer cells." (PMID 32499779, 2020). "Further understandings are needed to clarify the value of CCL2/CCR2 as a prognostic factor in many different cancer types." (PMID 31991604, 2020). "Many studies have reported that CCL2 can directly activate cancer cells through a variety of mechanisms." (PMID 33297571, 2020). "For this reason the use of anti-cancer antibodies against CCL2/MCP-1 increases the effectiveness of anticancer therapy." (PMID 32781743, 2020). "Mechanistically, the cancer-promoting roles of Wnt5a in TAMs depended on CaMKII-ERK pathway-mediated CCL2 secretion." (PMID 32140070, 2020). "Most of the genes in the subnetworks were inflammatory cytokines and participated in TNF signaling pathways and pathways in cancer, such as Ccl2, Ccl20, Csf1, Cx3cl1, Cxcl1, Cxcl3, Il6, Birc3, Map3k8, Nos2, Nfkb2, Tnfrsf1b, and Vcam1." (PMID 33042984, 2020). "CCL2, produced by both cancer and stromal cells, preferentially binds to CCR2, which is expressed to varying degrees in a wide range of organs and tissues including blood, brain, heart, kidney, liver, lung, ovary, pancreas, spinal cord, spleen, and thymus." (PMID 33247183, 2020). "CCL2, the central regulator of monocyte mobilization from the bone marrow, often shows higher serum levels in both mouse and human cancer." (PMID 33042791, 2020). "Then MSCs are recruited into contact with OS cells, trans-differentiate into cancer-fibroblasts, and secret more MCP-1(CCL2), GRO-α (CXCL1), TGF-β, IL-6, and IL-8 in the microenvironment." (PMID 32977425, 2020). "There is also compelling evidence for the targeting of CCL2/CCR2 in the treatment of various cancers." (PMID 33247183, 2020). "As a mediator of inflammation, CCL2 recruits inflammatory cells, modifying the environment in which cancer eventually develops." (PMID 32784743, 2020). "In parallel, CCL2 has elevated the levels of PCNA+ cancer cells and has also shifted the cell cycle from G2-M to G1-S in association with SRC and PKC activation in TNBC cells." (PMID 32582148, 2020). "Results from our group demonstrate the therapeutic potential of CCR2 as a novel target in treatment of PCa, and possibly other types of cancer, particularly in obese state with a host CCL2-stimulated environment." (PMID 32471499, 2020). "Taken together, these data suggest a strong rationale for investigating the efficacy of combination CCL2 inhibition with anti-PD-1 therapy in models of cancer." (PMID 33247183, 2020). "Then, CCL2 is secreted from these cancer cells and recruits CCR2+Ly6c+ inflammatory monocytes, resulting in differentiation into Ly6c-metastasis associated macrophage (MAM)." (PMID 31963413, 2020). "Further experiments revealed that the cancer-promoting functions of Wnt5a in TAMs were dependent on CCL2 secretion." (PMID 32140070, 2020).
cancer (continued). "Monocytes migrate into peritoneal lesions using the C-C chemokine ligand 2 (CCL2) derived from CAFs and differentiate into the M2 phenotype by macrophage colony-stimulating factor (M-CSF) and IL-6 secreted from CAFs and cancer cells." (PMID 33081727, 2020). "Oligo-Fucoidan can attenuate the negative effects of etoposide (ETO) chemotherapy that promotes IL-6 and MCP-1/CCL2 production in aggressive HCT116 cancer cells which activate Stat3 and Stat6 signaling, respectively." (PMID 32059469, 2020). "In brief, RB inactivation in several types of cancer cells enhances production of pro-inflammatory cytokines, including CCL2, through upregulation of mitochondrial reactive oxygen species (ROS) production." (PMID 32244804, 2020). "c-jun and c-Fos are target genes for the treatment of inflammation, cancer, and vascular reconstruction and can regulate the expression of many downstream genes, such as CCL2 and IL-1β." (PMID 33273957, 2020). "Cytokine/chemokine profiling of these MDSCs demonstrated that both myeloid cell subsets from cancer patients produced substantial amounts of CCL2, CCL3, CCL4, G-CSF, IL-8 and IL-6." (PMID 31811337, 2020). "In breast cancer, ZOL can significantly reduce the expression of cancer cell factors such as CCL2 and IDO to suppress regulatory T-cell function." (PMID 32974183, 2020). "On the other hand, in some cancers, e.g., in ovarian adenocarcinoma, the expression of CCL2 decreases." (PMID 33182504, 2020). "In comparison with Het-1A cells, CCL2 secretion in culture medium was markedly higher in TE-1 cancer cells, and the chemotaxis assay with human monocyte THP-1 cells indicated that monocyte migration was also increased in TE-1 conditioned medium." (PMID 32103760, 2020). "IHC results showed that the expression of FOXQ1, Twist1, and CCL2 in CRC tissues was significantly higher than that in para-carcinoma tissues." (PMID 33330033, 2020). "Collectively, these data suggest that a positive feedback loop between IL6 from TAMs and CCL2 from TAMs-educated CRC cells promotes the EMT of cancer cells and the recruitment of macrophages." (PMID 30927925, 2019). "The role of CCL2 has been of interest in cancer biology and the discovery of CCL2-mediated redistribution of ALIX can potentially have wide-ranging implications." (PMID 31172941, 2019). "Then, neutralizing TNFα in the co-culture or pretreatment of cancer cells with anti-TNFR1 mAb significantly decreased the production of CCL2." (PMID 31780645, 2019). "Osteoblastic CCL2 induced the migration of CCR2-expressing cancer cells and in this manner contributed to bone metastasis formation." (PMID 31572390, 2019). "CCL2 has been described as regulating migration and invasion in several cancer types, including OSCC." (PMID 30871117, 2019). "Despite several uncertainties, blockade of CCL2 has been reported to be beneficial in inhibiting metastasis of various cancer types in experimental models." (PMID 30871117, 2019). "GBM cells secreted CCL2 that increase cancer invasion, migration and cell growth in an autocrine manner." (PMID 31207928, 2019). "TNFα is a critical macrophage-produced mediator that elevates the production of CCL2 by multiple types of cancer cells." (PMID 31780645, 2019). "This expansion was associated with a significant increase in CX3CL1 and reduction of CCL2 in cancer patients' sera." (PMID 30930117, 2019). "Fucoidan supplementation increases cancer cell death and attenuates the adverse effects of etoposide that decrease the production of the pro-inflammatory cytokine IL-6 and chemokine CCL2/MCP-1." (PMID 31041568, 2019). "EMT program has been reported to stimulate the production of proinflammatory factors by cancer cells including CCL-2, and CCL-2 specifically has been demonstrated to induce EMT in cancer cells." (PMID 31130637, 2019).
cancer (continued). "Of note, the key role of CCL2 in cancer progression has been demonstrated by the direct correlation between its overexpression and poor prognosis characterizing many types of primary tumor." (PMID 31484464, 2019). "We previously showed that MCP-1 was also increased in the sera of the C26 cancer mice, and here we found that the expression of CCL2/MCP-1 in the tumors was associated with the levels of MCP-1 in sera (R = 0.485, p = 0.035)." (PMID 31731747, 2019). "Further, deletion of FBXW7 in bone-marrow-derived stromal cells (BMSCs) resulted in the accumulation of Notch which consequently rendered elevation of chemokine (C-C motif) ligand 2 (CCL2), thereby promoting cancer metastasis in vivo." (PMID 30791487, 2019). "CCL2's function of attracting monocytes is indispensable to get monocytes to the center of inflammation or cancer, and therefore, this property is a prerequisite for being able to exert other effects on those cells." (PMID 31921102, 2019). "Under GF-deprivation CCL2 is also known to suppress unwanted excessive autophagy and upregulates expression of proteins like survivin that confer a survival advantage to cancer cells." (PMID 31287009, 2019). "Increased activation of AKT-mTOR increases the phosphorylation levels of STAT3, leading to CCL2 expression and suppressing cancer immune reaction activation." (PMID 31781676, 2019). "Further loss-of-function studies revealed that silencing PIPKIγ greatly reduced CCL2 expression at both the mRNA and protein levels, leading to weak chemotaxis of cancer cells to macrophages." (PMID 31781676, 2019). "CCL2 blockade targeting myeloid cell infiltration has been successful in animal models of human cancers." (PMID 31552027, 2019). "Monocyte chemotactic and activating factor (CCL2) secreted by cancer cells and stroma recruits CXCR2+ positive monocytes and macrophages to enable seeding, colonization and outgrowth." (PMID 31447846, 2019). "Hypoxia promoted cancer cell production of more macrophage chemokines, and among all increased chemokines (CCL2, CCL5, CCL8, CCL19, CCL21, and CXCL1), CCL8 was the most increased according to qRT-PCR detection." (PMID 31263103, 2019). "It is well-established that CCL2 is a chemokine that is essential for the recruitment of macrophage cells, and FoxQ1 expressed in cancer cells has shown to increase attraction of macrophages through CCL2 production." (PMID 30927925, 2019). "Annexin A6 enriched tumor-derived Evs secreted from cancer cells treated with chemotherapeutic compounds taxanes and anthracyclines were found to promote cancer metastasis to lung by inducing the activation of NFκB and CCL2." (PMID 32010626, 2019). "The combination of CCL2 or CCR2 with antigen CA 15-3 resulted in an increase in the NPV in all stages of cancer." (PMID 30151375, 2018). "Q-RT-PCR of RNA isolated from FACS-sorted monocytes, macrophages, neutrophils, and HER2+ cancer cells during early stages of progression confirmed the CCL2 production by HER2+ early lesions, as detected by q-RT-PCR, IF analysis, and ELISA." (PMID 29295986, 2018). "Upregulation of CCL2 around HER2+ early cancer cells was also observed at the protein levels as confirmed by quantifying soluble CCL2 in the conditioned media of the early cancer cells by enzyme-linked immunosorbent assay (ELISA) and by IF analysis." (PMID 29295986, 2018). "Concerning CCL2, its production from different cell types, such as fibroblasts, OBLs, endothelial cells, and smooth muscle cells, is thought to promote cancer growth and metastasis." (PMID 30154786, 2018). "The relevance of the interplay between Notch and IL-1β is strengthened by the evidence that effective IL-1β and CCL2 antagonists are currently in clinical review to treat benign inflammatory disease, and their transition to the cancer clinic has been proposed." (PMID 30154786, 2018).